TLR4 (toll like receptor 4)
Diseases named in the same sentence as TLR4 in open-access papers (continued):
Sharing a sentence is not in itself a finding about the gene and the disease.
diabetic nephropathy (continued). "Although the literature data indicate a key role of TLR2 and TLR4 in the pathophysiology of diabetic nephropathy, the participation of other receptors is not excluded." (PMID 32933213, 2020). "These may suggest that Pg-LPS-induced diabetic nephropathy is mainly dependent on TLR2 signaling on glomerular endothelial cells, and that TLR4 blocker eritoran may play a role to slow the progress of diabetic nephropathy." (PMID 29018490, 2017). "In addition, the interplay of TLR4 signaling and the RAS might contribute to the pathogenesis of diabetic nephropathy." (PMID 37983238, 2023). "However the role of TLR4 in the complicated pathophysiology of diabetic nephropathy is not understood." (PMID 24842252, 2014). "HG conditions in diabetic kidney disease could induce the increased expression of TLR4, cleaved caspase‐1, GSDMD‐NT and secretion of IL‐1β, and IL‐18; pyroptosis in these HG conditions could be partly reversed by TLR4 inhibitors (TAK‐242) and NF‐κB inhibitors (parthenolide)." (PMID 34459122, 2021). "In the renal tubules of patients with diabetic nephropathy, TLR4 is upregulated, but TLR2 is not, and TLR4 deletion attenuated albuminuria, renal dysfunction, and renal cortical NF-κB in streptozotocin-induced diabetic mice." (PMID 27338360, 2016). "Similarly, in vivo data showed an increase in tubular TLR2, HMGB1, and fibronectin expression, with no increase in TLR4 expression, suggesting that the HMGB1-TLR2-NF-κB pathway might play a dominant role in mediating inflammation in diabetic nephropathy in the long term." (PMID 40584714, 2025).
influenza (94 papers, 2009 to 2026). An acute viral infection of the respiratory tract, occurring in isolated cases, in epidemics, or in pandemics; it is caused by serologically different strains of viruses (influenzaviruses) designated A, B, and C, has a 3-day incubation period, and usually lasts for 3 to 10 days. "Collectively, TLR4 plays a pathogenic role in the pathogenesis of influenza by recognizing a wide range of ligands from oxidized phospholipid to viral proteins." (PMID 36990977, 2023). "Collectively, these results show that M1 contributes to viral pathogenicity and aggravates lung damage caused by influenza infection, in which TLR4 serves as a critical component." (PMID 36990977, 2023). "Intranasal immunization with a split H3N2 vaccine plus a TLR-4 agonist induced polyfunctional Th17 cellular responses to exacerbate inflammation and increase weight loss and morbidity during early influenza infections." (PMID 33266210, 2020). "Gene-deficient TLR4 as well as gene-deficient RAGE mice are partially protected from influenza-induced lethality." (PMID 32380958, 2020). "Via TLR-2 and TLR-4, such vaccine formulation promoted the induction of robust Ab and Th1-/Th17-type cellular responses and when associated with inactivated Influenza vaccine, generated a protective immunity against Influenza challenge." (PMID 29563912, 2018). "Influenza-induced lethality is due to the TLR4-stimulating effects of TLR4 agonists damage-associated molecular patterns (DAMPs) which can stimulate monocyte-derived dendritic cells, inducing proinflammatory cytokine secretion and FP7 prevented DC activation by HMGB1." (PMID 33243230, 2020). "Therefore, FP7 can antagonize TLR4 activation in vitro and protect mice from severe influenza infection, most likely by reducing TLR4-dependent cytokine storm mediated by damage-associated molecular patterns (DAMPs) like HMGB1." (PMID 28106157, 2017). "Previous studies indicated that successfully blocking TLR4 signaling significantly reduces the pathogenesis associated with bacterial sepsis and lethal influenza infection indicating the critical role of this innate immune-signaling pathway in exasperating immunological responses." (PMID 28542576, 2017). "We have since shown that many TLR4 antagonists that are structurally unrelated to Eritoran and act by distinct mechanisms are highly effective therapeutically in influenza-infected mice and CR." (PMID 39699172, 2025). "Research indicates that adjuvants incorporating TLR4 agonists can enhance influenza vaccines by inducing cross-protective immunity." (PMID 41012165, 2025). "The synthetic combinations of TLR7 and TLR4 agonists, when administered with recombinant or chimeric hemagglutinin (rHA), significantly enhanced cross-protection against diverse influenza strains." (PMID 41012165, 2025). "Building on the success of TLR4 agonists in enhancing influenza vaccine efficacy, attention turned toward TLR7 agonists for their unique ability to activate antiviral innate immunity." (PMID 41012165, 2025). "A similar Th17 bias was reported with an intranasal subunit vaccine adjuvanted with CRX-601 (a synthetic TLR-4 agonist), where vaccine-induced Th17 responses exacerbated morbidity following influenza infection." (PMID 41050681, 2025). "The TLR4 agonist glucopyranosyl lipid adjuvant–stable emulsion (GLA-SE) can enhance T cell responses when combined with influenza split-virus vaccines (SVVs), significantly improving vaccine-mediated protection against influenza in older adults." (PMID 38892096, 2024). "Ex vivo PCLS experiments were performed to study the effects of enrichment treatment on mRNA responses of IL-8, IFN-β and TLR-4 in lung tissues to infections with A. pleuropneumoniae, swine influenza (SwIAV H3N2) or a combination of these." (PMID 39720408, 2024).
influenza (continued). "Preventive intranasal administration of the probiotic Lacticaseibacillus rhamnosus GG was demonstrated to impact Toll-like receptor (TLR4) signaling in a neonatal mouse model of influenza infection." (PMID 37299594, 2023). "Huoxiang Suling Shuanghua Decoction exerts an anti-influenza effect by affecting the expressions of mRNA and protein including TLR4, CD14, MyD88, NF-kB p65, HIF-1α, VEGF, IL17A, IL6, and inhibiting the accumulation of inflammation." (PMID 36386710, 2022). "In influenza and in some influenza like infections (such as SARS-CoV-2), genetic polymorphism of TIRAP, an accessory protein of TLR4, attenuates the function of TIRAP, leading to the reduced production of pro-inflammatory cytokines." (PMID 35629310, 2022). "For example, a novel influenza vaccine based on virosomes supplemented with the Toll-like receptor 4 (TLR4) ligand monophosphoryl lipid A (MPLA) and the metal ion-chelating lipid DOGS-NTA-Ni adsorbed into the membrane was recently developed." (PMID 35632575, 2022). "Overall, our results suggest that HSSD exerts pharmacological activity against influenza through multiple targets involved in TLR4/NF-κB p65 signaling pathway and the HIF-1α/IL17 signaling pathway." (PMID 36386710, 2022). "Research also reported that blocking TLR4 or CD14 in mice can protect against influenza-induced acute lung injury." (PMID 36386710, 2022). "While the TLR4/TRIF signaling axis was suggested to be central for ALI, MyD88 has also been implicated in the host response to influenza." (PMID 34282358, 2021). "Table I summarizes the various TLR4 antagonists and signaling inhibitors that have been shown to be efficacious against influenza infection in animal models and their mechanisms of action." (PMID 34282358, 2021). "Dong and colleagues have developed a novel influenza vaccine formulation consisting of virosomes with the Toll-like receptor 4 (TLR4) ligand monophosphoryl lipid A (MPLA) and the metal-ion-chelating lipid DOGS-NTA-Ni incorporated into the membrane." (PMID 34326849, 2021). "Additional explanations include polymorphisms in the toll-like receptor 4 gene (TLR4), involved in the innate immune system’s response to both bacterial pathogens and influenza." (PMID 33952233, 2021). "Together, these data strongly support the concept that influenza infection triggers TLR4-mediated inflammation leading to ALI." (PMID 34282358, 2021). "We found that lipidated imidazoquinolines TLR7/8 agonists can elicit a Th1-biased influenza specific immune response in mice and when combined with a TLR4 agonist, elicit a Th17 response as well." (PMID 32210973, 2020). "Therapy with the TLR4-blocking compound eritoran ameliorated murine influenza-induced lung injury by inhibiting the cytokine storm." (PMID 32380958, 2020). "Previous work has demonstrated the efficacy of using a TLR4 agonist in combination with a lipidated TLR7/8 agonist or a lipidated TLR7/8 agonist alone in protecting against influenza challenge either in a DMSO, liposome, or emulsion formulation." (PMID 32210973, 2020). "Successful preclinical treatment results using specific HMGB1-, TLR4- or RAGE-antagonists further support that the HMGB1/RAGE/TLR4-axis is central in the pathogenesis of influenza infections." (PMID 32380958, 2020). "Another study reported that tlr4 knockout mice are resistant to influenza-induced lung injuries and lethality, and this TLR4 inhibition-dependent protective effects is mimicked by LPS competitive antagonist eritoran." (PMID 32326516, 2020). "FP7 turned out to protect mice from acute lung injury (ALI), one of the most prominent influenza-related damages, and increase survival after viral infection with an efficiency similar to Eritoran, a well-established TLR4 antagonist developed by Eisai." (PMID 32765484, 2020). "As noted in "HIV virus’’ section, LPS activation of TLR4 leads to acute systemic sepsis, chronic inflammatory diseases particularly in viral infections such as influenza and HIV infection." (PMID 33243230, 2020).
influenza (continued). "Previous studies reported that influenza-induced lethality due to ALI was secondary to the cytokine storm triggered by the stimulation of TLR4 by host-derived DAMPs including OxPAPC and HMGB120,39." (PMID 28106157, 2017). "FP7 antagonizes both PAMP and DAMP triggering of TLR4, inhibiting cytokine production by monocytes and DCs in vitro and influenza-induced cytokine gene expression in vivo." (PMID 28106157, 2017). "In this study, we demonstrated intranasal vaccination with influenza antigens, and a novel synthetic TLR4-based adjuvant system provided protection against a lethal heterologous viral challenge." (PMID 24465206, 2014). "The comparison of the KEGG “Influenza” response pathway led to the identification of nodes targeted by C. burnetii and B. abortus to down-modulate TLR4/TLR3, STAT1 and type I IFN-responsive genes." (PMID 24915541, 2014). "To date, there have been few studies addressing the role of TLR4 adjuvants in vaccine-induced adaptive immunity against influenza, virus particularly following intranasal vaccination, and none have evaluated the existence or role of Th17 cells." (PMID 24465206, 2014). "We evaluated the efficacy of a synthetic toll-like receptor 4 agonist CRX-601 as an adjuvant for enhancing vaccine-induced protection against influenza infection." (PMID 24465206, 2014). "Using the mouse model of influenza infection, we evaluated the immunogenicity and efficacy of a fully synthetic TLR4 agonist, CRX-601, formulated for mucosal delivery." (PMID 24465206, 2014). "While it is clear that both VSV and influenza infections can involve TLR4, the cytosolic nucleic acid innate immune receptors play a large role in detecting RNA viruses and initiating an IFN response via the TBK-1/IRF3 axis." (PMID 23853595, 2013). "For most other licensed vaccines, there is only indirect evidence implicating TLR function: Hib-OMPC – TLR2, meningococcal – TLR2, pertussis – TLR4, influenza – TLR7, measles – TLR2/TLR4." (PMID 23565115, 2013). "To further advance development of such vaccines, we have analyzed the impact on immune responses of incorporating a stable oil-in-water emulsion and a synthetic TLR4 agonist into a standard influenza vaccine." (PMID 21060869, 2010). "TLRs, such as TLR3, TLR7, and TLR8, are membrane-bound PRRs that recognize viral RNA: TLR3 detects double-stranded RNA (dsRNA), a byproduct of influenza replication, TLR7/8 sense single-stranded RNA (ssRNA) from the viral genome, while TLR2 and TLR4 recognize influenza-induced DAMPs." (PMID 40692679, 2025). "In addition to MPL, other synthetic TLR4 agonists have been explored for their adjuvant potential in enhancing influenza vaccine efficacy." (PMID 41012165, 2025). "Having established that EC overexpression of Sparcl1 worsens viral pneumonia through TLR4 signaling, we next explored whether inhibition of TLR4 is sufficient to ameliorate influenza-induced injury in mice." (PMID 38762489, 2024). "It has been proven that administration of Eritoran protects mice from lethal influenza infection by blocking OxPAPC-dependent activation of TLR4 and that the harmful TLR4-mediated signaling can be inhibited also in this case by TLR4 antagonists directly interacting with MD-2." (PMID 36678520, 2022). "Thus, blocking TLR4 therapeutically during influenza infection not only mitigates influenza-induced disease, but also prevents an enhanced inflammatory response to secondary bacterial infection." (PMID 34282358, 2021). "While all of the studies presented above support a key role for TLR4 in influenza-induced disease, influenza does not express any TLR4 PAMPs, suggesting that a host-derived DAMP produced during influenza infection might actually signal through TLR4." (PMID 34282358, 2021). "The blocking of TLR4 to protect against more lethal strains of influenza has also been reported." (PMID 34282358, 2021).
influenza (continued). "The diversity of these various inhibitors of TLR4 signaling, coupled with the spectrum of mechanisms by which they act, strongly support the notion that TLR4 is key to the host inflammatory response to influenza infection." (PMID 34282358, 2021). "In this in vivo model of influenza infection, the use of the specific inhibitor of TLR-4 stimulation of human DCs resulted in the reduction of influenza virus-related lethality, proinflammatory cytokine gene expression in the lungs, and acute lung injury (ALI)." (PMID 32724296, 2020). "Interestingly, viruses can evade the host immune response, thereby enhancing viral replication, when TLR4 is inhibited, but TLR4 antagonists can protect mice from lethal influenza infection." (PMID 30337931, 2018). "Interestingly, viruses can evade the host immune response when TLR4 is inhibited, thereby enhancing viral replication, and one study has shown that a TLR4 antagonist can protect mice from lethal influenza infection." (PMID 30337931, 2018). "This may appear counterintuitive at first because the TLR4 pathway is often required for protection against influenza infection." (PMID 30337931, 2018). "TLR4 has also been linked to the induction of acute lung injury (ALI) during influenza infection, with exposure to influenza derived antigens inducing nicotinamide adenine dinucleotide phosphate oxidase-dependent production of reactive oxygen species which generate oxidized host phospholipids." (PMID 29552008, 2018). "Abrogation of TLR4 expression, either through administration of a therapeutic antagonist or use of tlr4−/− murine strains, provided protection against virally induced lung injury in mouse models of influenza infection." (PMID 29552008, 2018). "Interestingly, the TLR4 antagonist Eritoran protected mice from lethal influenza infection and blunted ALI38,39." (PMID 28106157, 2017). "Declining innate immune responses may decrease adjuvant responsiveness in the elderly, but TLR4 agonists have been shown to improve responses to influenza vaccines in both aged mice and aged humans." (PMID 25793508, 2015). "In addition, our results is strengthened by a recent report that TLR4−/− or TLR4 antagonist-treated mice are highly refractory to influenza-induced lethality, due to blocking inflammation by host-derived, oxidized phospholipid that potently stimulates TLR4." (PMID 25188232, 2014). "The aim of this study was to evaluate whether selected polymorphisms of TLR2, TLR3 and TLR4 influence the incidence and clinical picture of pandemic A/H1N1/2009 influenza." (PMID 23151015, 2012). "Combined, our present results suggest that the LPS of Prevotella spp., or other components present within this bacteria spp., inhibit the ability of Haemophillus influenza LPS to elicit complete TLR4 signaling hence leading to the reduction in IL-12p70 production by DCs." (PMID 22363778, 2012). "Similarly, specific activation of the TLR4 pathway with synthetic agonists protected mice against influenza-induced lethality." (PMID 21375734, 2011). "Importantly, influenza does not express “pathogen-associated molecular patterns” (PAMPs) that activate TLR4." (PMID 39699172, 2025). "However, we reasoned that influenza, which targets the lung and leads to a “cytokine storm,” might be more amenable to therapeutic TLR4 antagonism." (PMID 39699172, 2025). "In support of the observation that TLR4-/- mice are extremely refractory to influenza infection, other studies have subsequently shown that many TLR4 antagonists, that act by a variety of distinct mechanisms to prevent signaling all block influenza-induced lethality." (PMID 34282358, 2021). "Thus, it was hypothesized that blocking TLR4 signaling might represent a viable therapeutic approach for mitigating influenza-induced ALI." (PMID 34282358, 2021).